SLC30A10 (solute carrier family 30 member 10)
Description:
Calcium:manganese antiporter of the plasma membrane mediating the efflux of intracellular manganese coupled to an active extracellular calcium exchange. Required for intracellular manganese homeostasis, an essential cation for the function of several enzymes, including some crucially important for the metabolism of neurotransmitters and other neuronal metabolic pathways. Manganese can also be cytotoxic and induce oxidative stress, mitochondrial dysfunction and apoptosis. Could also have an intracellular zinc ion transporter activity, directly regulating intracellular zinc ion homeostasis and more indirectly various signaling pathway and biological processes.
Synonyms: ZnT-10; ZNT10; ZNT8; DKFZp547M236; ZRC1; HMDPC; HMNDYT1
Tractability: Antibody: UniProt places it where antibodies can reach, with high confidence; its Gene Ontology location is reachable by antibodies, with high confidence; UniProt predicts a signal peptide or a membrane-spanning region. PROTAC: its protein half-life has been measured.
Gene: Protein-coding gene on chromosome 1 (219,685,427 to 219,959,018, reverse strand). Ensembl gene ENSG00000196660.
Subcellular location: Cell membrane; Golgi apparatus membrane; Recycling endosome membrane; Early endosome membrane
Pathways (Reactome):
Transport of small molecules: Metal ion SLC transporters
Gene Ontology:
Molecular function: calcium:manganese antiporter activity; manganese ion transmembrane transporter activity; protein binding; zinc ion transmembrane transporter activity; monoatomic cation transmembrane transporter activity
Biological process: cellular response to angiotensin; epidermal growth factor receptor signaling pathway; intracellular copper ion homeostasis; intracellular manganese ion homeostasis; intracellular zinc ion homeostasis; manganese ion export across plasma membrane; manganese ion transport; positive regulation of ERK1 and ERK2 cascade; zinc ion import into organelle; detoxification of zinc ion; metal ion transport; zinc ion transmembrane transport; manganese ion homeostasis; monoatomic cation transport; transmembrane transport
Cellular component: early endosome; early endosome membrane; Golgi apparatus; Golgi membrane; lysosomal membrane; plasma membrane; recycling endosome; recycling endosome membrane; synaptic vesicle; transmembrane transporter complex; membrane; cytoplasmic vesicle; vesicle membrane
Genetic constraint (gnomAD): Loss-of-function variants: 10 observed, 17.13 expected, observed/expected ratio (o/e) 0.58, 90% interval 0.36 to 0.99. The upper end of that interval is the gene's LOEUF score, 0.99, which puts it in group 4 of 6, group 1 being the genes least tolerant of losing a copy. Missense variants: 521 observed, 620.14 expected, observed/expected ratio (o/e) 0.84, 90% interval 0.78 to 0.9. Synonymous variants: 272 observed, 262.54 expected, observed/expected ratio (o/e) 1.04, 90% interval 0.94 to 1.14.
Homologues: Orthologues: chimpanzee SLC30A10 (99% identical), macaque SLC30A10 (96% identical), rabbit SLC30A10 (82% identical), dog SLC30A10 (79% identical), mouse Slc30a10 (78% identical), rat Slc30a10 (77% identical), guinea pig SLC30A10 (68% identical), tropical clawed frog slc30a10 (51% identical), zebrafish slc30a10 (40% identical), Drosophila melanogaster ZnT63C (28% identical), Drosophila melanogaster ZnT35C (17% identical), Drosophila melanogaster ZnT33D (16% identical). Paralogues in human: SLC30A1 (34% identical), SLC30A5 (20% identical), SLC30A7 (19% identical), SLC30A8 (17% identical), SLC30A4 (16% identical), SLC30A2 (16% identical), SLC30A3 (16% identical), SLC30A6 (15% identical).
Diseases named in the same sentence as SLC30A10 in open-access papers:
SLC30A10 is named in the same sentence as 72 diseases in open-access papers, as found by Europe PMC text mining. Sharing a sentence is not in itself a finding about the gene and the disease. The quoted sentences say what the papers report.
Dystonia (28 papers, 2012 to 2025). An abnormally increased muscular tone that causes fixed abnormal postures. "Rare genetic variants in SLC30A10 or SLC39A14 have been linked to hypermanganesemia with dystonia and neurotoxicity." (PMID 41178719, 2025). "Mutation of the SLC30A10 results in Mn accumulation and parkinsonism with dystonia, polycythemia, and liver cirrhosis." (PMID 40278159, 2025). "Mutations in SLC30A10 lead to a syndrome of hypermanganesemia with dystonia, polycythemia, and chronic liver disease, referred to as hypermanganesemia with dystonia 1 (HMNDYT1) (OMIM#613280)." (PMID 40278159, 2025). "One is referred to as hypermanganesemia with dystonia, polycythemia, and cirrhosis (HMNDYT1, MIM 613280), which is caused by mutations in the SLC30A10 gene." (PMID 36733764, 2022). "Recent studies have linked a rare genetic disorder linked to mutation of the SLC30A10 gene, where the loss of function mutation of SLC30A10 results in a syndrome of hepatic cirrhosis, hypermagnesemia, dystonia, polycythemia resulting in familial parkinsonism." (PMID 33072457, 2020). "The syndrome of hepatic cirrhosis, dystonia, polycythemia, and hypermanganesemia caused by SLC30A10 mutation is a treatable inherited metal deposition syndrome." (PMID 31288771, 2019). "Mutations in SLC30A10 lead to a syndrome of hypermanganesaemia with dystonia, polycythaemia and chronic liver disease, now referred to as hypermanganesaemia with dystonia 1 (HMNDYT1) (OMIM #613280)." (PMID 31089831, 2019). "It ameliorated dystonia and parkinsonism in SLC30A10 mutated patients, and its efficacy proved to be persistent over time is some cases with long-term follow-up." (PMID 29382362, 2018). "Recent studies found that mutations in the human SLC30A10 gene, which encodes a manganese (Mn) efflux transporter, are associated with hypermanganesemia with dystonia, polycythemia, and cirrhosis (HMDPC)." (PMID 28692648, 2017). "A homozygous mutation of the Mn transporter SLC30A10 causing severe hypermanganesemia, dystonia, parkinsonism, polycythemia, and chronic hepatic disease has recently been described." (PMID 25117825, 2014). "New subtypes of neuronal brain iron accumulation have been delineated and linked to mutations in C19orf12 and WDR45, while a new treatable form of dystonia with brain manganese deposition related to mutations in SLC30A10 has been described." (PMID 23757263, 2013). "Mutations in the SLC30A10 gene, encoding a manganese transporter, cause a syndrome of hepatic cirrhosis, dystonia, polycythemia, and hypermanganesemia." (PMID 22926781, 2012). "Physicians should be familiar with the clinical presentation of these disorders as the underlying cause of dystonia/parkinsonism and look for other accompanying features, such as liver disease and polycythemia, which are typically associated with SLC30A10 mutations." (PMID 40278159, 2025). "Patients with SLC30A10 deficiency develop Mn excess, dystonia, liver disease, and polycythemia." (PMID 38336290, 2024). "Impaired function of the manganese transporter SLC30A10 has been implicated in HMDPC (hypermanganesemia with dystonia, polycythemia, and cirrhosis), an early-onset metabolic disorder clinically characterized by increased systemic Mn levels, neurological impairment, polycythemia, and hepatic injury." (PMID 28692648, 2017). "Finally, given the recent identification of a new form of treatable dystonia caused by brain manganese deposition secondary to mutations in SLC30A10, serum manganese measurement should at least be considered." (PMID 23775978, 2013). "This systematic review explores the genotype–phenotype correlations of GLB1, SLC6A3, SLC30A10, PLA2G6, and SLC39A14—recently classified as DYT SLC39A14 and historically linked to dystonia-parkinsonism." (PMID 40362326, 2025).
Dystonia (continued). "Loss-of-function mutations in SLC30A10 have been reported to cause a rare recessive syndrome, hypermanganesemia with dystonia 1 (HMNDYT1), characterized by cirrhosis, dystonia, parkinsonism, polycythemia, and hypermanganesemia." (PMID 34315874, 2021). "Recently, a gene named SLC30A10 (solute carrier family 30 member 10) was identified in patients with hepatic cirrhosis, dystonia, polycythemia, and hypermanganesemia, concomitant with high Mn brain levels." (PMID 25136353, 2014). "In addition, mutations in ZNT2/SLC30A2 result in transient neonatal zinc deficiency (TNZD) in breastfeeding infants of affected mothers, whereas ZNT10/SLC30A10 mutations cause Parkinsonism and dystonia with hypermagnesemia, polycythaemia, and hepatic cirrhosis." (PMID 30237557, 2018). "Our analysis showed dystonia-parkinsonism predominates in SLC6A3 and PLA2G6, while GLB1, SLC30A10, and SLC39A1 show predominantly dystonic phenotypes with a low frequency of parkinsonism." (PMID 40362326, 2025). "Biallelic variants in SLC30A10 cause a syndrome marked by early-onset dystonia, parkinsonism, hepatic cirrhosis, polycythemia, and hypermanganesemia (hypermanganesemia with dystonia, DYT/PARK-SLC30A10, OMIM#613280)." (PMID 40724495, 2025). "With the exception of SLC6A3 and PLA2G6, which primarily manifest with dystonia and parkinsonism as key features, we found that GLB1, SLC30A10, and SLC39A14 predominantly exhibit a dystonic phenotype, sometimes accompanied by other movement disorders, such as parkinsonism or ataxia." (PMID 40362326, 2025). "In 2016, a comparable hereditary Mn transporter defect known as hypermanganesemia with dystonia 2 (HMNDYT2) (OMIM #617013) was reported, which can be differentiated from SLC30A10 deficiency by the lack of liver involvement and polycythemia." (PMID 40278159, 2025). "However, we observed that the proportion of individuals manifesting parkinsonism in GLB1, SLC30A10, and SLC39A14 is lower than expected under the DYT/PARK nomenclature, where dystonia and parkinsonism should generally coexist or be prominent features in approximately half or more of the patients." (PMID 40362326, 2025).
Parkinsonism (28 papers, 2013 to 2026). Characteristic neurologic anomaly resulting from degeneration of dopamine-generating cells in the substantia nigra, a region of the midbrain, characterized clinically by shaking, rigidity, slowness of movement and difficulty with walking and gait. "Second, we found no apparent accumulation of Mn—which has been shown to cause parkinsonism symptoms—in the brain in Slc39a11 knockout animals for Slc30a10 and Slc39a14 knockout animals." (PMID 39114488, 2024). "Brain Mn accumulation with parkinsonism is also observed in patients harboring loss-of-function mutations in the Mn efflux transporter SLC30A10 (also known as ZNT10) and the uptake transporter SLC39A14 (also known as ZIP14)." (PMID 37482277, 2023). "Manganese-induced Parkinsonism result from a combination of chronic exposure (occupational or environmental) and genetic susceptibility (SLC30A10 mutation)." (PMID 34316640, 2020). "Several studies linked a manganese transporter SLC30A10, which was found in this study to be involved in baseline refractive development, to parkinsonism, thus implicating this gene in the regulation of dopamine signaling." (PMID 31362747, 2019). "Most significantly, hypermanganesemia with associated Parkinson Disease symptoms has been found related to mutations in the SLC30A10, a member of the SLC30 solute carrier subfamily previously thought to serve as a specific Zn transporter." (PMID 26471164, 2016). "The mutations of CDF family member, SLC30A10, were reported to cause parkinsonism." (PMID 35860667, 2022). "Until now mutations in SLC30A10 are the only genetic factor known to be associated with a familial Manganese-induced Parkinsonism, and these results highlight the importance of SLC30A10 and efflux in regulating Manganese levels at the cellular and organismal level." (PMID 34316640, 2020). "Importantly, these recent discoveries involving SLC30A10 and its mutations reinforce its crucial role in humans as a Mn transporter, broadening our understanding of familial Parkinsonism as a result of SLC30A10 mutations." (PMID 31293375, 2019). "Impaired hepatic and enterocytic manganese uptake (SLC39A14) and excretion (SLC30A10) lead to deposition of manganese in the basal ganglia resulting in childhood-onset dystonia-parkinsonism." (PMID 40320765, 2025). "This review on GLB1, SLC6A3, SLC30A10, SLC39A14, and PLA2G6 is the third MDSGene review series on DYT/PARK genes, following previous articles on DRD genes and X-linked dystonia-parkinsonism." (PMID 40362326, 2025). "Homozygous mutations of this family of transporters (SLC30A10, SCL39A8, SLC39A14) cause a rare pediatric genetic disease characterized by hypermagnesemia, parkinsonism and dystonia, liver disease and polycythemia, and specific imaging signs." (PMID 37627255, 2023). "However, subsequent case reports, including those reviewed in our study, have shown that, similar to SLC30A10, parkinsonism is a much less common symptom." (PMID 40362326, 2025). "Additionally, the nominal enrichment for Parkinson’s disease genes, among surface area–immune genes, included the gene SLC30A10." (PMID 37348803, 2024). "Clinical cases of parkinsonism have been described in relation to the homozygous mutations in the solute carrier (SLC) transporters, which mediate the influx (SLC39A8, SLC39A14) and efflux (SLC30A10) of Mn." (PMID 37627255, 2023). "Given the predominantly neurological presentation of these conditions, it is likely that missing data on cardinal signs/symptoms, such as parkinsonism in GLB1, SLC30A10, and SLC39A14, reflect their actual absence." (PMID 40362326, 2025).
polycythemia (22 papers, 2012 to 2025). Abnormally high mass or concentration of red blood cells in the blood, either due to an increase in erythropoiesis or a decrease in plasma volume. "To further investigate the basis of EPO excess and polycythemia in SLC30A10 deficiency, we interrogated SLC39A14." (PMID 38652538, 2024). "SLC30A10 deficiency impairs gastrointestinal Mn excretion, resulting in severe Mn excess as well as neurologic and liver dysfunction, polycythemia, and erythropoietin (EPO) excess." (PMID 38652538, 2024). "This suggested that Mn excess plays a causal role in Epo excess and polycythemia in Slc30a10–/– mice." (PMID 38652538, 2024). "This suggested that SLC39A14-dependent import of Mn into liver drives EPO excess and polycythemia in SLC30A10 deficiency." (PMID 38652538, 2024). "SLC30A10 deficiency results in impaired gastrointestinal manganese excretion, leading to manganese excess, neurologic deficits, liver cirrhosis, polycythemia, and erythropoietin excess." (PMID 38652538, 2024). "To determine if Mn excess contributed to Epo excess and polycythemia in mutant mice, we weaned Slc30a10–/– mice onto Mn-deficient diets and measured liver Mn levels, liver Epo RNA levels, and red blood cell (RBC) counts in 6-week-old mice." (PMID 38652538, 2024). "Hepatocyte Hif2a deficiency corrects Epo excess and polycythemia and attenuates Mn levels and aberrant liver gene expression in Slc30a10–/– mice." (PMID 38652538, 2024). "Although a role for HIFs in EPO excess and polycythemia in SLC30A10 deficiency has yet to be explored, several studies have shown links between Mn, EPO, and HIFs." (PMID 38652538, 2024). "This indicated that Slc39a14 is also essential for aberrant expression of several hypoxia-regulated genes and polycythemia in Slc30a10 deficiency." (PMID 38652538, 2024). "The transcription factor HIF-2 is a key determinant of manganese excess, erythropoietin excess, and polycythemia in SLC30A10 deficiency, which underlies inherited manganese excess." (PMID 38652538, 2024). "The observation that hepatic Hif2a deficiency attenuates Epo excess and polycythemia in Slc30a10–/– mice is consistent with a previous study showing that hepatic Epo expression is regulated by Hif2a, not Hif1a." (PMID 38652538, 2024). "In contrast to SLC39A14 deficiency, SLC30A10 deficiency results in polycythemia and excess levels of erythropoietin, a hormone that stimulates RBC synthesis." (PMID 34051234, 2021). "Our results suggest that polymorphism in SLC30A10 is a risk factor for manganese-induced hepatocellular damage, polycythemia, and iron anemia in a much broader population beyond the rare recessive syndrome HMNDYT1." (PMID 34315874, 2021). "Slc39a14 deficiency corrects liver Epo excess and polycythemia in Slc30a10–/– mice." (PMID 38652538, 2024). "Overall, characterization of mice with Slc39a14 and Slc30a10 deficiency indicated that Slc39a14 is essential for development of liver Mn excess, Epo excess, and polycythemia in Slc30a10–/– mice." (PMID 38652538, 2024). "To determine if Hif1 and/or Hif2 contribute to Epo excess and polycythemia in Slc30a10–/– mice, we applied 2 approaches, 1 short-term and the other long-term." (PMID 38652538, 2024). "While deficiency in SLC30A10 or SLC39A14 leads to neurological deficits, only SLC30A10 deficiency causes liver cirrhosis and polycythemia." (PMID 38336290, 2024). "Slc30a10–/– mice develop Mn-dependent Epo excess and polycythemia." (PMID 38652538, 2024). "Other genetic mutations, such as SLC30A10, have also been associated with polycythemia without elevated EPO levels." (PMID 39767963, 2024). "Hepatic Hif2a deficiency corrected erythropoietin expression and polycythemia and attenuated aberrant hepatic gene expression in Slc30a10-deficient mice, while hepatic Hif1a deficiency had no discernible impact." (PMID 38652538, 2024).
polycythemia (continued). "Unlike SLC39A14 deficiency, SLC30A10 deficiency causes erythropoietin excess and polycythemia, although the link between Mn excess and erythropoietin excess has yet to be firmly established." (PMID 34051234, 2021). "(In contrast, unlike SLC39A14 deficiency, SLC30A10 deficiency also leads to liver cirrhosis and polycythemia." (PMID 34051234, 2021). "However, none had polycythemia or liver disease, as is typically observed in patients with SLC30A10 pathogenic variants." (PMID 36138644, 2022). "The absence of polycythemia and the rarity of cognitive or psychiatric symptoms help differentiate this disease from SLC30A10-related hypermanganesemia and acquired hypermanganesemia, respectively." (PMID 40362326, 2025). "Overall, these analyses indicated that the decrease in tissue Mn levels in Slc30a10–/– Hif2afl/fl Alb mice was due to a decrease in parenchymal Mn content, not in correction of polycythemia." (PMID 38652538, 2024). "Unlike SLC30A10 deficiency, SLC39A14 deficiency does not produce liver dysfunction, polycythemia, or EPO excess)." (PMID 38652538, 2024). "Mn excess in Slc30a10–/– mice develops at 14–21 days of life, and polycythemia develops at 21–28 days of life (data not shown)." (PMID 38652538, 2024). "Despite the presence of polycythemia in Slc30a10–/– Hif1afl/fl and Slc30a10–/– Hif1afl/fl Alb mice, neither total nor nonheme iron levels were increased in livers from these mice relative to their Slc30a10+/+ counterparts." (PMID 38652538, 2024). "Unlike SLC30A10 deficiency, SLC39A14 deficiency does not produce liver disease, polycythemia, or EPO excess." (PMID 38652538, 2024). "Similarly, despite the presence of polycythemia in Slc30a10–/– Hif2afl/fl mice, neither total nor nonheme iron levels were increased in livers from these mice relative to Slc30a10+/+ Hif2afl/fl mice." (PMID 38652538, 2024). "Mutations in the cellular Mn export protein SLC30A10 lead to Mn excess, dystonia, Parkinsonism, polycythemia, and chronic liver disease, while mutations in the cellular Mn import protein SLC39A14 lead to a similar disease albeit without polycythemia and liver disease." (PMID 28617866, 2017).